CD4 (CD4 molecule)
Diseases named in the same sentence as CD4 in open-access papers (continued):
Sharing a sentence is not in itself a finding about the gene and the disease.
tuberculosis (continued). "Whereas tuberculosis is a recommended indication for initiation of HAART at any CD4 count, the WHO guidelines state that “there are limited data on the initiation of ART in patients with TB and CD4 counts of >350 cells/mm3”." (PMID 21234380, 2011). "The AIDS Clinical Trials Group recently completed a study entitled “A Strategy Study of Immediate Versus Deferred Initiation of Antiretroviral Therapy for HIV Infected Persons Treated for Tuberculosis With CD4 Less Than 200 Cells/mm3”." (PMID 21234380, 2011). "HIV preferentially infects and kills CD4+ T lymphocytes, resulting in the loss of cell-mediated immunity and a high probability that the host will develop opportunistic infections including tuberculosis (TB)." (PMID 22164280, 2011). "Stratification into these subpopulations was only feasible in individuals who had PPD reactive CD4 T-cell frequencies above the detection limit (23 of 24 patients with active tuberculosis and 23 of 28 patients with successfully treated tuberculosis)." (PMID 21423578, 2011). "Protective immunity to tuberculosis (TB) is conferred by IFN-γ producing TH1 CD4 and effector CD8 T cells." (PMID 21298114, 2011). "Estimated rates of tuberculosis using simulated data and different methods to estimate the time-point of change of CD4+ count." (PMID 22114687, 2011). "Person-time, rates of tuberculosis and hazard ratios for tuberculosis using clinical cohort data and different methods to estimate the time-point of change of CD4+ count." (PMID 22114687, 2011). "Patients co-infected with tuberculosis tended to start cART at higher CD4 cell counts, possibly reflecting earlier diagnosis of HIV in symptomatic patients." (PMID 21504595, 2011). "The CD4 cell count plays an important role in the clinical manifestations of tuberculosis in HIV-infected patients." (PMID 21731675, 2011). "Median T-lymphocyte CD-4 count was lower at the time of diagnosis in HIV-coinfected patients who died during tuberculosis treatment as compared with HIV-coinfected patients who survived (68 versus 105 respectively, p = 0.06)." (PMID 21199579, 2011). "In addition to the early impact of HIV seroconversion on immune containment of M. tuberculosis, the risk of TB disease continues to rise as CD4 cell counts decrease." (PMID 20936108, 2011). "In studies of M. tuberculosis vaccines, our group recently showed that the anti-tuberculosis protective responses evoked by immunization were also related to the induction of double-positive IFN-γ/TNF-α expressing CD4 T cells." (PMID 22205939, 2011). "The objective was to study the capacity of a new biomarker, the expression of the T cell maturation marker CD27 on MTB-specific CD4 T cells, to identify active tuberculosis (TB) disease in subjects from a MTB and HIV endemic region." (PMID 22087280, 2011). "Her HAART regimen was continued and she improved after commencement of anti-tuberculosis drugs, with evidence of progressive increase in CD4 cell count." (PMID 22355437, 2011). "Person-time, tuberculosis rates and hazard ratios by CD4+ stratum were compared using all available CD4+ counts (measurement frequency 1–3 months) and 6 monthly measurements from a clinical cohort." (PMID 22114687, 2011). "Our finding that 60% of potential CD4+ T-cell epitopes in PPE18 are unconserved is consistent with previous research that has found the PPE gene family to be particularly variable among tuberculosis isolates." (PMID 20353587, 2010). "Preventing the transmission of HIV-1 and preserving pathogen-specific immunity in those already infected with HIV-1 (by initiating ART at higher CD4+ counts) will likely reduce the incidence of tuberculosis." (PMID 20353569, 2010). "According to the national protocols for administering antiretrovirals (ARVs), 18% of the participants were on ARVs while the remaining participants were either on therapy for tuberculosis (TB) or their CD4 count was still in the normal range." (PMID 20411682, 2010).
tuberculosis (continued). "Only a lower CD4+ stratum at tuberculosis diagnosis remained significant in multivariate analysis (aHR = 1.5, 95% CI = 1.1-2.2)." (PMID 20353569, 2010). "The evidence increasingly suggests that if the future is to be different, we have to intervene with treatment far earlier, before people living with HIV fall into or spend too long in the CD4+ "death zone" for tuberculosis." (PMID 20205768, 2010). "Adults with HIV infection were eligible for monthly food rations if they had any one of: tuberculosis, body mass index (BMI) <18.5kg/m2, CD4 cell count <350/mm3 (in the prior 3 months) or severe socio-economic conditions." (PMID 20796284, 2010). "Due to the observational nature of our study, we were unable to compare the incidence of clinical deterioration after ART initiation in two groups of tuberculosis patients: those with a CD4+ count of 200-350 cells/μL and those with a CD4+ count < 200 cells/μL." (PMID 20353569, 2010). "Conversely, both of the less acute bacterial infection patient groups showed normal CD8+ T activation, but an increased level in the CD4+ T cells, with significance for the Tb (tuberculosis) group at p < 0.02." (PMID 20626864, 2010). "Given the possibility that human Th1, Th2, Th17 and Treg cells play a role in immune regulation of tuberculosis, it is important to determine the evolution and interrelation of these CD4 T cell populations in primary M. tuberculosis infection." (PMID 19730727, 2009). "While CD4 T cells are well described for their protection against tuberculosis, little is known about the role of human CD8 T cells in anti-tuberculosis immunity." (PMID 19381260, 2009). "Studies in mice and HIV-infected humans indicate that CD4 T cells are of central importance for immune protection against tuberculosis." (PMID 19730727, 2009). "Our studies represented the first elucidation of kinetics for tetramer-bound epitope-specific CD4 T cells in animal models of tuberculosis/vaccination." (PMID 19730727, 2009). "An increase in peripheral CD4+CD25+Foxp3+ T cells has been observed in a number of infectious diseases including tuberculosis, hepatitis C and helminth infections, as well as human and murine malaria infection." (PMID 19680449, 2009). "The low diagnostic accuracy of these clinical criteria and of CD4 cell count emphasizes the urgent need for availability of HIV PCR testing in low resource countries and for better diagnostic tools for tuberculosis in young children." (PMID 19390690, 2009). "The current work represents a first extensive experimental study of epitope-specific CD4 T cells using class II MHC/peptide tetramer in animal models of tuberculosis." (PMID 19730727, 2009). "HIV-infected persons are eligible for ART after counseling, clinical examination, and if immunologic criteria are met; for those with tuberculosis, CD4 cell count <350/ml indicates ART eligibility." (PMID 19543396, 2009). "Bronchoalveolar lavage (BAL) of patients with pulmonary tuberculosis has shown increases in inflammatory cytokines and percent CD4+ cells compared to uninfected controls, and in advanced, cavitary tuberculosis markers of effective immunity are reduced." (PMID 19753300, 2009). "Our overall study is focused on ambulatory HIV-infected persons with CD4 = 200 residing in an area with endemic tuberculosis." (PMID 18325120, 2008). "Modeling suggests that ART will result in greater reductions in tuberculosis incidence if started at CD4 cell counts of 500 cells/μl, but guidelines in Brazil and most countries recommend initiating treatment later." (PMID 18781195, 2008). "Patients lost to follow-up differed from those who remained in care by site, baseline CD4 cell count and the presence of active tuberculosis." (PMID 21532891, 2008). "The goal of this work was to establish a new biomarker for clinical tuberculosis based on measurable changes that TB specific CD4 T-cells undergo as they differentiate in response to virulent mycobacteria." (PMID 17710135, 2007).
tuberculosis (continued). "In South Africa, the incidence of tuberculosis among HIV infected individuals rises above that seen in the rest of the population once CD4 counts fall below 350 cells/μl, and ART reduces this incidence by up to 90%." (PMID 17555564, 2007). "In 27 subjects diagnosed with active tuberculosis, the median [range] percentage of interferon-gamma synthetic CD4+ lymphocytes was 2.77% [0–23.93%] versus 0% [0–2.10%] in 15 negative for active infection (p<0.0001)." (PMID 18092001, 2007). "Patients commencing ART with CD4 50–199 cells/μl had 9.7 clinic visits, 0.6 days in hospital and 0.06 cases of tuberculosis." (PMID 17147833, 2006). "Extrapulmonary tuberculosis presents more frequently in patients with CD4 counts less than or equal to 100 × 106/L." (PMID 16269085, 2005). "However, it was previously stated that to treat tuberculosis, CD4+ Th1 cells and CD8+ cytolytic lymphocytes must be activated." (PMID 40771802, 2025). "Effective tuberculosis control requires CD4+ T cell recognition of infected macrophages." (PMID 40990918, 2025). "However, in low-tuberculosis-incidence European countries, immunocompromised patients have a relatively low risk of active tuberculosis unless there is a clear history of exposure to M. tuberculosis and ongoing HIV replication with low CD4 counts." (PMID 41450573, 2025). "Other reason for this finding in our study could be attributed to the fact related to variations in the impact of DTG on weight gain, which could depend on factors such as sex, baseline BMI, CD4 count, and tuberculosis coinfection." (PMID 40920752, 2025). "This implies that the delayed priming of CD4+ T cells during tuberculosis may result from Mtb residing in anatomical compartments that are not transferred from the lungs to the lymph nodes." (PMID 40825006, 2025). "Additionally, increased expression of immune checkpoint molecules, such as BTLA, on CD4+ T cells is observed in patients with tuberculosis, which often correlates with disease progression." (PMID 40141021, 2025). "However, the risk is increased in PLHIV with detectable HIV-replication and low CD4-counts, especially when they originate from a country of medium- or high tuberculosis incidence." (PMID 40823191, 2025). "Furthermore, in peripheral blood mononuclear cells (PBMC) from tuberculosis patients, blocking of IL-10 resulted in higher lytic activity of CD4+ and CD8+ cells." (PMID 40939292, 2025). "In patients with tuberculosis, especially against the background of comorbidities, such as diabetes, there is a change in the frequency of CD4+ T-cell subtypes, including an increase in the number of central memory T-cells and a decrease in the number of naive and effector memory T-cells." (PMID 40141021, 2025). "However, human tuberculosis control requires the activation of CD4+ Th1 cells and CD8+ cytolytic lymphocytes." (PMID 40771802, 2025). "Although CD4+/CD8+ T cells have a protective role in human tuberculosis and other infections, the role of γδ T cells is unknown." (PMID 38741147, 2024). "The increasedactivation of CD4+ T cells may be attributed to tuberculosis-immunereconstitution inflammatory syndrome (TB-IRIS) with concurrent cART + 3HP." (PMID 39257997, 2024). "Patients who had no tuberculosis were 1.33 times at risk of dying before attaining CD4 count recovery [aSHR 1.33; 95% CI (0.96–1.85)] compared to those who had tuberculosis." (PMID 39058196, 2024). "L. loa has moreover been associated with higher frequency of other filarial and human T-lymphotropic virus (HTLV) infections, as well as impaired CD4+ memory T cell responses to tuberculosis antigen, suggesting a state of immunosuppression that extends to bystander-antigens." (PMID 38771861, 2024). "HIV patients with low CD4 counts are at high risk of developing tuberculosis compared to individuals without HIV infection." (PMID 39058196, 2024).
tuberculosis (continued). "Interestingly, we also found that NLR, MLR, SII, EOS%, and CD4/CD8 have predictive value for DILI in HBsAg-positive tuberculosis patients (P < .05)." (PMID 39533543, 2024). "“We really need to expand LTBI (latent tuberculosis infection) test coverage in the country as we realize that on a daily basis, those with a CD4 lower than 350, who should receive treatment, don’t do so and then the patient starts developing tuberculosis, right?”." (PMID 39602400, 2024). "However, the susceptibility to tuberculosis disease increases in the early years after HIV infection, far before decreases in CD4 cells below 500 cells/μL, which reveals that the mechanisms of increased susceptibility go beyond the depletion of CD4 cells." (PMID 38675837, 2024). "This study aimed to investigate the relationship between pro- and anti-inflammatory CD4+ cytokine production following stimulation with two types of latency-associated Mycobacterium tuberculosis (M.tb) antigens to allow differentiation between active TB and LTBI." (PMID 39257584, 2024). "The risk of developing tuberculosis among HIV-positive children on ART was 2.22 times (AHR = 2.22; 95%CI: 1.65–2.79) whose CD4 count below the threshold (<200 cells/mm3) than children who had greater (≥200 cells/mm3) (I2 = 51.21%, p<0.001) and with no publication bias (p = 0.5623)." (PMID 38968268, 2024). "This study found that retroviral-infected patients receiving HAART treatment were at increased risk for severe hepatotoxicity if they were co-infected with hepatitis B virus or hepatitis C virus, co-infected with tuberculosis or had a CD4+T-cell count below 200 cells/mm3." (PMID 38605149, 2024). "Consequently, changes in TLR expression can lead to alterations in the count of CD4+ lymphocytes, which are of chief importance in the pathogenesis of HIV infection and tuberculosis, affecting the risk of developing these diseases." (PMID 37606452, 2023). "Furthermore, among the 18 individuals who tested positive for tuberculosis, CD4 cell count assessments were conducted in 15 cases." (PMID 37667708, 2023). "Th1 and Th17 cells are the main effector CD4+ T cells in tuberculosis." (PMID 37686061, 2023). "We used South African guideline definitions of viremia, retention in care, and viral suppression and adjusted for potential confounders of clinical outcomes after viremia, such as age, gender, active tuberculosis disease, time period of viremia, viral load, and CD4 count." (PMID 38045558, 2023). "So, you could bundle it: every 6 months, the doctor will order the viral load, CD4 and tuberculosis tests, understand?" (PMID 36962892, 2023). "The CD4+ T cells play a major role in the anti-tuberculosis immune response." (PMID 37103584, 2023). "These deaths occur primarily in individuals with advanced HIV disease (AHD) who have a CD4 count of less than 200 cells/μL and are vulnerable to potentially fatal opportunistic infections such as tuberculosis and cryptococcal meningitis, and malignancies such as lymphoma." (PMID 38106376, 2023). "Both patient groups that were compared were well matched for factors that can confound glucose metabolism such as sex, BMI, alcohol consumption, physical exercise, renal function, tuberculosis status, CD4 + cell count as well as HIV virologic suppression at 24 weeks." (PMID 37577475, 2023). "Moreover, it is the protective cellular immunity against tuberculosis that is mainly mediated by CD4+ T-lymphocytes but supported by CD8+ T-lymphocytes." (PMID 37761328, 2023). "It is well known that HIV may attack an individual’s immune system by destroying CD4 cells and weakens immunity against important opportunistic infections, including tuberculosis, severe bacterial infections, and some cancers." (PMID 36873867, 2023). "We found that 22.1% of patients had a CD4+ T cell count of 51-200 pieces/μL, and the Food and Drug Administration showed weak drug interactions between clarithromycin, rifabutin, and the three prophylactic anti-tuberculosis drugs." (PMID 37651639, 2023).
tuberculosis (continued). "From a molecular perspective, it makes sense to assume that anti-exhaustion medications will enhance the immune response to tuberculosis because T-cell exhaustion has been demonstrated to limit the functionality of ESAT-6-specific CD4 T cells during M. tuberculosis infection." (PMID 36674038, 2023). "CD4+ Tcm cells, with superior proliferation capacity, are required for long-lasting immunity and are induced by vaccination strategies, including those against influenza and tuberculosis." (PMID 36987861, 2023). "It is therefore assumed that peripheral blood CD4+CD25+CD127low Tregs expression may be a promising marker for auxiliary diagnosis of tuberculosis." (PMID 36035072, 2022). "Tuberculosis was predominant in all subgroups stratified by CD4 counts." (PMID 35042469, 2022). "However, one previous study recommends that tuberculosis patients initiate ART according to different levels of CD4+ T-cell count." (PMID 36008855, 2022). "However, the absolute number and the frequency of Th1 cells within the CD45RA–CCR7+CXCR5+ CD4+ T cells compartment were significantly lower in patients with tuberculosis when compared to a healthy control, while the relative number of Tfh2 cell was increased." (PMID 36761174, 2022). "However, AFRICOS participants had significantly higher rates of CD4<200 and tuberculosis and significantly lower rates of obesity, DM, hepatitis C coinfection and syphilis." (PMID 35377881, 2022). "Finally, we examined the ex vivo transcriptional profiles of SGL-specific T cells in patients with active tuberculosis and found canonical transcription factor lineages among CD4 and CD8 CD1b-restricted T cells." (PMID 35013257, 2022). "Studies have shown that Rhodiola Rosea can increase the CD4/CD8 ratio in the peripheral blood of patients with tuberculosis, which might be responsible for alleviating TB symptoms after treatment." (PMID 36120339, 2022). "This study aimed to evaluate whether calcitriol supplementation enhances CD4+ T cell count and prognosis in patients with tuberculosis and low 25(OH)D levels." (PMID 35513795, 2022). "However, in the multivariate analysis, individuals with CD4 counts < 50 cells/mm3 were 2.88 (95% CI: 1.41, 5.89; p value < 0.01) times more likely to develop tuberculosis." (PMID 35042469, 2022). "For example, in South Africa, a significantly greater proportion (73%) of patients viewed their CD4, viral load, and/or tuberculosis results within seven days via USSD on their mobile phones compared to patients who had to return to the clinic to retrieve their results (8.6%)." (PMID 33772406, 2021). "In addition to the discovery cohort, a validation cohort of patients with HIV-1 admitted to hospital with CD4 counts less than 350 cells per μL and a high clinical suspicion of new tuberculosis were recruited." (PMID 34386782, 2021). "In cases of CD4+ T lymphocytes equal to or greater than 50 cells/mm3, antiretroviral therapy may be started up to the eighth week, close to the start of tuberculosis treatment maintenance stage." (PMID 34008717, 2021). "As the infection progresses, there is a gradual drop of CD4+ T lymphocytes, with intermittent infection emergence, which may have atypical presentations, or past infection reactivation, such as tuberculosis and herpes zoster." (PMID 34008717, 2021). "Tuberculosis is one of the opportunistic infections that occur at any CD4 count in HIV patients." (PMID 34863200, 2021). "Advanced pretreatment clinical stage, low baseline CD4 T cell count, and diagnosis of tuberculosis (TB) after ART initiation had a higher risk of non-responsiveness and lower response rate to ART." (PMID 33684169, 2021). "Another study from South Africa found that people with HIV on antiretroviral therapy (ART) with normal CD4 counts had four times the risk of tuberculosis than people without HIV." (PMID 32967690, 2020). "The immune response against tuberculosis relies, at least in part, on CD4+ T cells." (PMID 31908851, 2020).